EZH2 (enhancer of zeste 2 polycomb repressive complex 2 subunit)
Diseases named in the same sentence as EZH2 in open-access papers (continued):
Sharing a sentence is not in itself a finding about the gene and the disease.
cancer (continued). "In this review, we have summarized emerging evidence showing that EZH2 is expressed in cancer, and most of the immune cells forming the TME." (PMID 36135315, 2022). "Inhibition of EZH2 activity induced cell death in malignant rhabdoid tumor (MRT, SMARCB1-deficient cancer) cell line." (PMID 35806102, 2022). "EZH2 enhances cancer metastasis by regulating epithelial-mesenchymal transition and tumor angiogenesis via paracrine circuits." (PMID 36086687, 2022). "Overexpression of EZH2 is found in different types of cancer, and recurrently, amplification was present in AM (14.4%, 0.8%)." (PMID 35229492, 2022). "They found that UFC1 targets PTEN through the induction of EZH2 while the knockdown (KO) of UFC1 inhibits cancer proliferation and induces apoptosis and cell-cycle arrest." (PMID 35327612, 2022). "In the next section, we examine the role of lncRNAs in regulating EZH2 expression in various cancers." (PMID 35236381, 2022). "These feedback loops are in favor of cancer malignancy and further complicates molecular pathways related to circRNA/EZH2 axis." (PMID 35236381, 2022). "Overexpressed EZH2 and H3K27me3 abnormalities have been reported in various cancer types, although they appeared to be less dependent than in hematological tumors." (PMID 36239901, 2022). "The S-adenosylmethionine (SAM)-competitive inhibitors are among the common EZH2 inhibitors in cancer therapy." (PMID 35236381, 2022). "It exerts anticancer effects in many cancers including blood and solid cancers through inhibiting EZH2 or other methyltransferase activity." (PMID 35627217, 2022). "Stratified by survival, HCC ranked 36th, with statistical significance of the prognostic value of EZH2 in cancer types at p < 0.001." (PMID 35208478, 2022). "Various studies have elucidated the complex role of EZH2 in biological processes and cancer-related events." (PMID 35432300, 2022). "The data strongly suggested that the YY1-regulated EZH2 activity plays a dominant role in promoting cancer progression." (PMID 35406384, 2022). "Previous studies have described the transcription factor c-Myc also regulating EZH2 expression in various cancers, as well as in embryonic stem cells." (PMID 35565249, 2022). "Paradoxically, we identify a critical function of EZH2 in human cancers is to stabilize MYC-family oncoproteins and sustain MYC(N) dependent transcriptional amplification independent of its methyltransferase activity." (PMID 35013218, 2022). "Collectively, these findings reveal the complicated layers involved in the regulation of SMAD3 activation coordinated by EZH2-mediated SMAD3 K53/K333 methylation to drive cancer metastasis." (PMID 35085106, 2022). "Our finding that EZH2-92aa suppressed NKG2D ligand expression on GSCs suggested a mechanism by which cancer cells evade NK cell toxicity." (PMID 35970825, 2022). "Taken together, our study provides evidence to support a role of lncRNA SNHG6-miR101 axis in tamoxifen resistance of ER-positive breast cancers which involves modulation of EMT and cancer stem cells phenotype through targeting of ZEB1/EZH2." (PMID 36212408, 2022). "Several studies have confirmed that EZH2 expression is abnormally elevated in cancer tissues and is positively correlated with the degree of malignancy of cancer." (PMID 35784574, 2022). "Pan-cancer analysis revealed that EZH2 mRNA expression levels varied across 28 different types of cancer, excluding those for which normal tissue data were unavailable." (PMID 36358967, 2022). "In the present review, our aim is to provide a mechanistic discussion of ncRNAs role in regulating EZH2 expression in different cancers." (PMID 35236381, 2022). "The previous section highlighted the role of miRNAs as upstream mediators of EZH2 in cancer regulation." (PMID 35236381, 2022). "There have been various promising examples of the development of protein methyltransferase inhibitors for cancer therapy, such as EZH2 and PRMT5 inhibitors, and some have undergone clinical trials." (PMID 36421786, 2022).
cancer (continued). "Targeting PRC2 function (mainly by inhibiting EZH2 with small molecules) for cancer treatment has been extensively studied, and specific inhibitors have been developed for testing in clinical trials." (PMID 36612203, 2022). "Silencing EZH2 by using specific siRNA triggers the apoptosis of cancer cells and increased sensitivity to cisplatin chemotherapy." (PMID 36077660, 2022). "In BM, cancer cells overexpress an epigenetic modification protein, Enhancer of Zeste Homolog 2 (EZH2), and change its function from a methyltransferase to a transcription factor that increases the expression of c-JUN." (PMID 35884845, 2022). "Overall, EZH2 is a critical player in cancer and can affect proliferation, metastasis, and therapy response of cancer cells." (PMID 35236381, 2022). "EZH2 has been identified as a critical downstream component of the retinoblastoma tumor suppressor protein (pRB)–E2F pathway, which is essential for cancer cell proliferation and growth." (PMID 36009484, 2022). "EZH2 is a well-known oncogene in many cancers, and its overexpression is correlated with poor prognosis in GC patients." (PMID 35466313, 2022). "EZH2 inhibition was suggested as a promising approach for preventing the transition to advanced cancer stages." (PMID 35163453, 2022). "EZH2-mediated gene-silencing and other epigenetic mechanisms in cancer development and progression have gained increasing interest and offer new treatment options." (PMID 35740494, 2022). "Systematically, findings have signified that MINCR/EZH2 axis contributes to the rapid growth of the cells, cell invasion, and also apoptosis in the cancer cells." (PMID 34923811, 2022). "Further, SNHG6 silencing reduced cancer stem cell markers Sox2, Oct4 and EZH2 in T47DTR cells, relative to parental T47D cells, and anti-miR-101 oligomers significantly (p<0.01) attenuated this effect." (PMID 36212408, 2022). "EZH2, the enzymatic subunit of PRC2, is recurrently mutated and highly expressed in numerous cancers." (PMID 35563864, 2022). "Overexpression of EZH2 in cancer cells results in transcriptional repression through increased H3K27me3 activity." (PMID 35464847, 2022). "Other approaches to inhibiting PRC2 activity in cancer include a staple peptide inhibitor that disrupts the protein-protein interaction (PPI) of EZH2-EED, with significant antiproliferative functions even in cells resistant to EZH2 inhibitors." (PMID 36076977, 2022). "FBW7 is a well-known E3 ligase that degrades multiple proteins, including Myc, JUN, Nothc1 and EZH2, in cancer cells." (PMID 35081978, 2022). "Although a substantial amount of the literature suggests the beneficial effects of EZH2 inhibition in combination with cisplatin therapy in different cancer types, reports exist documenting the inverse relationship of EZH2 and cisplatin resistance." (PMID 36230683, 2022). "SOX5 also regulates a variety of targets in cancers, including EZH2, twist 1, P2RY8, MITF, and others." (PMID 35880568, 2022). "Pharmacological inhibition of EZH2 is under intensive investigation for combating cancers with aberrant PRC2 activity." (PMID 35137163, 2022). "LINC00628 has been reported to inhibit the malignant progression of cancer through different mechanisms, such as binding to EZH2 to regulate the p57 or H3K27me3 level, and interacting with the promoter of LAMA3 or VEGFA." (PMID 35350786, 2022). "The EZH2 unit of the PRC2 complex is responsible for the repression of tumor suppressor genes and is frequently overexpressed in cancers, therefore EZH2 is currently being investigated in cancer therapy research." (PMID 35563709, 2022). "Small-interfering RNA (siRNA) and short-hairpin RNA (shRNA) are synthetic, short ncRNAs capable of reducing EZH2 expression and suppressing cancer progression." (PMID 35236381, 2022).
cancer (continued). "LSD1 inhibitors are undergoing phase 2 clinical trials for other cancer types, and multiple small-molecular EZH2 inhibitors have been approved and/or are in clinical trials for other cancer types." (PMID 36212399, 2022). "Together, our data from both MBA-MD-231 and 4T1 cells showed that EZH2 promoted cancer cell migration and invasion, but this function is unlikely dependent on EZH2’s methyltransferase activity." (PMID 35538070, 2022). "In our study, we aimed to target MTHFD and EZH2 as a therapeutic approach for NSCLC cancer patients and further studies will address the mechanism behind their action." (PMID 35888776, 2022). "As EZH2 overexpression is common in many cancers, pharmacological inhibition has become a major area of interest in cancer research." (PMID 36359771, 2022). "EZH2 and PD-L1 are both immune checkpoints, which have diverse and complex effects on the occurrence and development of cancer." (PMID 36552722, 2022). "At the same time, the inhibition of target gene EZH2 plays a role as a cell cycle regulator, inhibiting cancer cell proliferation." (PMID 35164166, 2022). "The overexpression of EZH2 allows cancer cells to divide uncontrollably and plays an important role in the acquired chemoresistance of cancer cells." (PMID 36142846, 2022). "EZH2, an epigenetic regulator, is frequently upregulated in cancers which, in general, potentiates cancer cell malignant behavior." (PMID 36230683, 2022). "Secondly, EZH2 was upstream protein involved in cancer initiation, progression, metastasis, metabolism, drug resistance and immunity regulation." (PMID 35902797, 2022). "Four single-nucleotide polymorphisms (SNPs) of EZH2 (rs6950683, rs2302427, rs3757441, and rs41277434) were analyzed by real-time PCR genotyping in 176 patients with TNBC and 1000 cancer-free controls." (PMID 35813302, 2022). "The SUZ12, REST, and EZH2 genes were reported to contribute to the stemness of cancer cells, and they exhibited higher expression levels in the higher NAS group." (PMID 36309750, 2022). "The current study used Oncomine database to analyse the difference in EZH2 expression between carcinomas and normal samples." (PMID 35659256, 2022). "The attempts have already made to downregulate the expression of EZH2 gene through miRNA 26a resulting in increased apoptosis and inhibited cancer cell proliferation." (PMID 34094648, 2021). "We found that there exists a correlation between EZH2 expression and the pathological stages of cancers, including ACC, KICH, PAAD, KIRC, LIHC, and THCA (all P < 0.05)." (PMID 34381492, 2021). "The major findings of the current work are (a) E.C.M. detached cancer cells induces EZH2 expression and activity." (PMID 33531586, 2021). "A decrease in EZH2 expression can cause an increase in RKIP expression, making it possible for the loss of EZH2 expression in cancer cells to be caused by a gain of RKIP expression." (PMID 34944867, 2021). "EZH2 is positively related to cancer cell proliferation and localizes at the replication fork in response to DNA damage 135-138." (PMID 34671219, 2021). "Increased EZH2 in cancer cells after chemotherapy activated the transcription factor STAT3 and bound to the promoter regions of miR-378a-3p and miR-378d." (PMID 33823894, 2021). "SCIRT was reported to play a crucial role in cancer cell state transitions by direct interaction with chromatin modifier EZH2, then inhibiting cancer cells' self-renewal process." (PMID 34349799, 2021). "EZH2 is known as a target for cancer therapy, and different types of EZH2 inhibitors have been developed." (PMID 33974569, 2021).
cancer (continued). "As an important component of polycomb group proteins (PcGs), EZH2 has been confirmed to be overexpressed in a variety of cancer types with lethal outcomes, including OC cases." (PMID 34551671, 2021). "A number of studies have demonstrated that EZH2 and G9a are involved in the regulation of immune responses in both normal and cancer cells." (PMID 33436557, 2021). "Due to its high expression in several cancer cells and the downstream of pPB-E2F pathway, EZH2 is universally recognized as a marker of proliferation and a bona fide oncogene." (PMID 33761979, 2021). "We report here that the PRC2 complex is physically associated with ubiquitin-specific protease USP7 in cancer cells where USP7 acts to deubiquitinate and stabilize EZH2." (PMID 33849069, 2021). "EZH2 has been involved in several cancers and in particular in the regulation of skeletal myogenesis and in RMS pathogenesis." (PMID 34067464, 2021). "H3K27ac coinhibition augmented the efficacy of EZH2 inhibitors and also triggered the MAPK pathway in some cancers, signifying that the blockade of EZH2 resulted in a feedback stimulation of certain signaling pathways in a context-dependent manner." (PMID 34745848, 2021). "Our finding showed that cases with higher expression EZH2 had a poor prognosis for cancers of ACC, LGG, and LIHC." (PMID 34381492, 2021). "Expression analysis of treated tumors identified decreased expression of pediatric cancer markers and EZH2 targets, only after combined treatment, supported by Co-IP experiments confirming an interaction of PRC2 together with HDAC1 and 2 in EwS cells." (PMID 34654445, 2021). "Considering these contradictory results, the role of EZH2 in cytokine production by CD8+T cells need to be placed in each concrete cancer environment." (PMID 34737746, 2021). "The important role of EZH2 in many types of cancer has triggered interest in therapies targeting EZH2, and several small molecule inhibitors of EZH2 have recently been developed." (PMID 34815475, 2021). "In recent years, the pivotal role of EZH2 in various cancers has been noticed due to its vital function on mediating the histone methyltransferase activity of PRC2." (PMID 34257531, 2021). "HHEX caused a repression of a series of neural stemness genes or/and genes promoting cancer, Sox1, Sox2, Myc, Cdh2, Vim, Hes1, Zic1, Pax6, Ezh2, and Lsd1." (PMID 34595169, 2021). "For example, EPZ-6438 (an EZH2 inhibitor that represses PRC2 activity) inhibits the proliferation of cancer cells in haematological malignancies and induces apoptosis by restoring the expression of pro-apoptotic factors (such as FBXO32)." (PMID 34298745, 2021). "Splendid positive correlations were found between the MIAT and EZH2 expression in types of cancer in TCGA data." (PMID 34811354, 2021). "As research progresses, an increasing number of studies have reported that post-translational modifications (PTMs) of EZH2 play key roles in EZH2 biological functions in cancer progression." (PMID 34775498, 2021). "In order to confirm EZH2 as a therapeutic target for the E.C.M. detached cancer cells, we decided to use an EZH2 methyltransferase activity inhibitor, namely GSK343, which is known to efficiently inhibit the activity of EZH2." (PMID 33531586, 2021). "It was testified that Ezh2 promoted cell proliferation, migration, invasion and metastasis of cancer cells." (PMID 35003347, 2021). "Elevated levels of H3K27me3 and EZH2 often are present in many types of cancer and contribute to the development of malignancy." (PMID 34968294, 2021). "In cancer cells, under normoxia, EZH2 is recruited directly to the HIF-1α promoter and inhibits HIF-1α expression, whereas under hypoxia, this inhibitory effect is weakened, leading to unregulated HIF-1α expression." (PMID 34737746, 2021). "Recent studies have also indicated that NEAT1 activates the WNT/β-catenin pathway through binding to EZH2 and then facilitates cancer progression." (PMID 34769497, 2021).
cancer (continued). "EZH2 is the functional enzymatic component of the polycomb repressive complex 2 (PRC2)and it has been linked to many forms of cancer." (PMID 33650817, 2021). "Immunohistochemical staining (IHC) analysis demonstrated the clear upregulation of USP7 and EZH2 accompanied by the downregulation of FOXO1 in these cancer tissues compared to the normal tissues." (PMID 33849069, 2021). "A growing body of evidence indicated that increased activity of PRC2 or EZH2 was responsible for malignant phenotypes of cancer cells." (PMID 33779563, 2021). "Emerging evidence points toward a critical role for Enhancer of Zeste Homolog 2 (EZH2) in cancer cell proliferation and survival." (PMID 33803922, 2021). "These cancers have loss of H3K27me2 in addition to H3K27me3, indicating different mechanistic outcomes compared to EZH2 mutant cancers." (PMID 34617019, 2021). "In total, EZH2 positivity was found in 75.2% of 1603 analyzable cancers, including 63.1% tumors with weak, 8.0% with moderate, and 4.1% with strong immunostaining according to our criteria." (PMID 32303902, 2021). "The expression of EZH2 was associated with the CD8+, tregs, macrophage, and cancer-associated fibroblast infiltration in some tumors." (PMID 34381492, 2021). "According to the expression levels of EZH2, the cancer cases were divided into high-expression and low-expression groups." (PMID 34381492, 2021). "Overall, we showed that EZH2 induction is critical for the survival and sphere formation of E.C.M. detached cancer cells." (PMID 33531586, 2021). "Consistently, EZH2 has been demonstrated to promote cancer cell proliferation, migration, invasion, and metastasis through regulating the expression of a large array of target genes." (PMID 34065631, 2021). "Off note, treatment of an ErbB2 driven mouse model with an inhibitor of EZH2 revealed strong synergy with anti-ErbB2 targeted therapy which highlights the importance of EZH2 in several cancers and emphasizes its clinical relevance." (PMID 33235291, 2021). "Over the last decade, numerous studies have demonstrated that increased expression of EZH2 is a common denominator of multiple cancers promoting uncontrolled cell proliferation, at least in part, through transcriptional repression of critical target genes." (PMID 33803922, 2021). "This deemed EZH2 a relevant target in cancer therapies attempting to improve T cell recruitment into the TME." (PMID 34944867, 2021). "These include connecting cancers with HRD or STAG2 deficiency with PARP inhibitors, epigenetic dysregulation with histone deacetylase or EZH2 inhibitors, and DNA checkpoint abnormalities with ATM or ATR inhibitors, to name a few." (PMID 34101093, 2021). "It is also possible that the impairment of CD8 T cell function by Ezh2 targeting varies among different cancer types." (PMID 33403469, 2021). "The epigenetic regulator enhancer of zeste homolog 2 (EZH2) that is usually overexpressed in many cancers is the catalytic subunit of polycomb repressive complex 2 (PRC2), functioning as a methyltransferase to induce the trimethylation of histone H3 at Lys27." (PMID 34575883, 2021). "EZH2 has been linked to abnormally silenced genes via hypermethylation and depletion of EZH-induced cancer cell growth arrest in multiple myeloma." (PMID 33430434, 2021). "Both Yin Yang 1 (YY1) and enhancer of zeste homolog 2 (EZH2) are oncogenes with overexpressed statuses in cancers." (PMID 34065631, 2021). "All these findings extended our understanding of lncRNAs involved in EZH2 transcription, and suggested new therapeutic targets in cancer therapies." (PMID 34512145, 2021). "To investigate the role of EZH2 in LINC-PINT regulating cancer development, we measured the impact of LINC-PINT on EZH2 expression." (PMID 34257531, 2021). "Recently, studies have shown that the enhancer of zeste homolog 2 (EZH2) is an important regulator of the development of cancer development and progression." (PMID 33791221, 2021).